ZNF655 (zinc finger protein 655)
Description:
Probable transcription factor.
Synonyms: VIK; VIK-1
Tractability: Antibody: the Human Protein Atlas places it where antibodies can reach. PROTAC: UniProt records ubiquitination sites on it; ubiquitination databases record sites on it.
Gene: Protein-coding gene on chromosome 7 (99,558,406 to 99,576,453, forward strand). Ensembl gene ENSG00000197343.
Subcellular location: Nucleus
Subcellular location (Human Protein Atlas): Nucleoplasm; Plasma membrane
Pathways (Reactome):
Gene expression (Transcription): Generic Transcription Pathway
Gene Ontology:
Molecular function: protein binding; DNA-binding transcription factor activity, RNA polymerase II-specific; RNA polymerase II cis-regulatory region sequence-specific DNA binding
Biological process: negative regulation of G1/S transition of mitotic cell cycle; regulation of transcription by RNA polymerase II
Cellular component: cytoplasm; nucleolus; nucleoplasm; nucleus; plasma membrane
Genetic constraint (gnomAD): Loss-of-function variants: 3 observed, 11.37 expected, observed/expected ratio (o/e) 0.26, 90% interval 0.12 to 0.68. The upper end of that interval is the gene's LOEUF score, 0.68, which puts it in group 2 of 6, group 1 being the genes least tolerant of losing a copy. Missense variants: 526 observed, 601.25 expected, observed/expected ratio (o/e) 0.87, 90% interval 0.81 to 0.94. Synonymous variants: 178 observed, 205.65 expected, observed/expected ratio (o/e) 0.87, 90% interval 0.76 to 0.98.
Homologues: Orthologues: chimpanzee ZNF655 (100% identical), macaque ZNF655 (97% identical), guinea pig ZNF655 (85% identical), rabbit ZNF655 (82% identical), mouse Zfp655 (81% identical), dog ZNF655 (81% identical), rat Zfp655 (80% identical), pig ZNF655 (68% identical). Paralogues in human: ZNF189 (36% identical), ZNF658 (36% identical), ZNF28 (36% identical), ZNF7 (36% identical), ZNF708 (36% identical), ZNF229 (36% identical), ZNF30 (36% identical), ZNF182 (36% identical), ZNF41 (36% identical), ZNF585B (36% identical), ZNF484 (35% identical), ZNF534 (35% identical), and 164 more.
Diseases named in the same sentence as ZNF655 in open-access papers:
ZNF655 is named in the same sentence as 14 diseases in open-access papers, as found by Europe PMC text mining. Sharing a sentence is not in itself a finding about the gene and the disease. The quoted sentences say what the papers report.
glioma (7 papers, 2021 to 2024). A benign or malignant brain and spinal cord tumor that arises from glial cells (astrocytes, oligodendrocytes, ependymal cells). "For example, ANKHD1 and LINC00346 are elevated, whereas ZNF655 is reduced in glioma-associated endothelial cells." (PMID 34803608, 2021). "At the same time, linc00346 can lower the stability of ZNF655 and promote its mRNA degradation, resulting in low expression of zinc finger protein 655 (ZNF655) and weakened inhibition of glioma angiogenesis." (PMID 38967893, 2024). "In glioma-derived endothelial cells, Stau1 binds to the ZNF655 mRNA coding for a zinc finger protein following enhanced expression of the lncRNA LINC00346 and thus enhances its degradation via enhanced SMD." (PMID 35008641, 2021). "In addition, ZNF655 directly binds to the ANKHD1 promoter region to inhibit its transcription, further forming an ANKHD1/LINC00346/ZNF655 feedback loop, which can regulate glioma angiogenesis through messenger RNA decay mediated by Staufen1." (PMID 38967893, 2024). "The transcription factor ZNF655 promoted glioma progression by binding to the promoter of AURKA." (PMID 36518188, 2022). "Thus the ANKD1/LINC00346/ZNF655 feedback loop regulates glioma angiogenesis." (PMID 34803608, 2021). "Furthermore, the promoter region of ANKHD1 was targeted by ZNF655 and formed the feedback loop of ANKHD1/LINC00346/ZNF655 that regulated the angiogenesis of adult glioma cells." (PMID 37444408, 2023).
Alzheimer disease (2 papers, 2019 to 2020). A progressive, neurodegenerative disease characterized by loss of function and death of nerve cells in several areas of the brain leading to loss of cognitive function such as memory and language. "KEGG enrichment analysis showed that co-expressed genes of ZNF655 were significantly enriched in protein processing in the endoplasmic reticulum, spliceosome pathway, and some disease pathways, including Huntington’s, Parkinson’s and Alzheimer’s disease." (PMID 32328087, 2020).
basal cell carcinoma (1 paper, 2025). A carcinoma involving the basal cells. "ZNF655 was enriched in KEGG pathways including basal cell carcinoma, calcium signaling pathway, cardiac muscle contraction, juvenile diabetes mellitus, and neuroactive ligand receptor interaction." (PMID 40924716, 2025).
breast carcinoma (1 paper, 2021). "Of the remaining 12 genes, seven (A4GALT, C2ORF74, HRCT1, ZC4H2, ZNF512, ZNF655, and ZNF608) show similar relative expression profiles in large patient samples and other breast cancer cell lines thereby giving insight into predicted role of H3K4me3 mediated gene regulation via the miRNA-mRNA axis." (PMID 34261302, 2021).
colorectal cancer (1 paper, 2020). A primary or metastatic malignant neoplasm that affects the colon or rectum. "Hypermethylated genes were observed across the four cancers, such as ZNF655, RB1, and TFDP2, which have previously been reported to be epigenetic diagnostic biomarkers for various cancers (including breast and colorectal cancers)." (PMID 33143142, 2020).
pancreatic cancer (1 paper, 2022). "The biological effects of ZNF655 in pancreatic cancer cells was investigated by loss/gain-of-function assays in vitro and in vivo." (PMID 35927248, 2022). "In this study, the clinic value, biological function and underlying mechanisms of Zinc finger protein 655 (ZNF655) in human pancreatic cancer were evaluated." (PMID 35927248, 2022). "At present study, we evaluated the expression level, biological function and underlying mechanisms of ZNF655 in human pancreatic cancer." (PMID 35927248, 2022). "The expression level of ZNF655 in pancreatic cancer was determined by immunohistochemistry (IHC) staining." (PMID 35927248, 2022). "As the expression of ZNF655 increased, the survival time was shortened, suggesting that higher expression of ZNF655 predicted a worse prognosis in patients with pancreatic cancer." (PMID 35927248, 2022). "High expression of ZNF655 was observed in 21 of 66 low-grade pancreatic cancer (WHO II; 13.13%) and in 22 of 31 high-grade pancreatic cancer (WHO III–IV; 70.97%), suggesting that increased ZNF655 expression was found in higher tumor grade." (PMID 35927248, 2022). "Functionally, ZNF655 knockdown inhibited the biological progression of pancreatic cancer cells, which was characterized by weaken proliferation, enhanced apoptosis, arrested cell cycle in G2, impeded migration, and suppressed tumor growth." (PMID 35927248, 2022). "ZNF655 expression was significantly elevated in human pancreatic cancer and possessed clinical value in predicting poor prognosis." (PMID 35927248, 2022). "Subsequently, knockdown of ZNF655 in PANC-1 and SW1990 cells was used to investigate the role of ZNF655 in pancreatic cancer." (PMID 35927248, 2022). "Mechanically, these data suggested that ZNF655 facilitated malignant behaviors of pancreatic cancer cells via promoting the binding of E2F1 to CDK1 promoter." (PMID 35927248, 2022). "The downstream mechanism of ZNF655 regulating pancreatic cancer progression was preliminarily investigated and found that knockdown of ZNF655 downregulated CDK1." (PMID 35927248, 2022). "ZNF655 knockdown can promote the apoptosis of pancreatic cancer cells, which required the co-participation of a series of pro-apoptotic and anti-apoptotic factors." (PMID 35927248, 2022). "ZNF655 was abundantly expressed in pancreatic cancer, and its high expression was significantly correlated with poor prognosis." (PMID 35927248, 2022). "In fact, ZNF655 knockdown by shRNA specifically enhanced the apoptotic sensitivity of pancreatic cancer cells, while ZNF655 overexpression resulted in reduced apoptotic capacity." (PMID 35927248, 2022). "Taken together, these data suggested that ZNF655 facilitated malignant behaviors of pancreatic cancer cells via promoting the binding of E2F1 to CDK1 promoter." (PMID 35927248, 2022). "In this study, we found that that malignant progression of ZNF655 knockdown pancreatic cancer cells was significantly inhibited, which was characterized by weaken proliferation, impeded migration, arrested cell cycle in G2 and enhanced apoptosis." (PMID 35927248, 2022). "In order to further determine the biological functions of ZNF655 in human pancreatic cancer, a series of cell functional experiments were carried out in vitro." (PMID 35927248, 2022). "To clarified the clinical relevance of ZNF655 in the progression of human pancreatic cancer, we first examined expression level of ZNF655 in primary pancreatic cancer samples by IHC staining." (PMID 35927248, 2022). "The signal expression intensity of ZNF655 in pancreatic cancer tissues was significantly higher than that in adjacent normal pancreatic tissues." (PMID 35927248, 2022). "Collectively, ZNF655 expression was significantly elevated in human pancreatic cancer and had clinical value in predicting poor prognosis." (PMID 35927248, 2022).
pancreatic cancer (continued). "The promotive role of ZNF655 in pancreatic cancer via CDK1 was determined, which drew further interest regarding its clinical application as a promising therapeutic target." (PMID 35927248, 2022). "A significant finding of this study is the identification of a promoting role of ZNF655 in human pancreatic cancer." (PMID 35927248, 2022). "According to the eighth edition of the American Joint Committee on Cancer (AJCC) and the Union for International Cancer Control (UICC), the clinical relevance between ZNF655 and clinicopathological characteristics of pancreatic cancer patients was analyzed." (PMID 35927248, 2022). "Furthermore, knockdown of CDK1 alleviated the promoting effects of ZNF655 overexpression in pancreatic cancer cells." (PMID 35927248, 2022). "Additionally, the mRNA expression level of ZNF655 in pancreatic cancer cell lines PANC-1 and SW1990 was significantly higher than that of normal pancreatic cell line HPDE6-C7." (PMID 35927248, 2022). "ZNF655 facilitated malignant behaviors of pancreatic cancer cells via promoting the binding of E2F1 to CDK1 promoter, which may contribute to the development of promising targets for tumor diagnosis and treatment." (PMID 35927248, 2022). "Reduced expression of ZNF655 resulted in reduced malignant phenotypes in pancreatic cancer cells." (PMID 35927248, 2022). "Additionally, knockdown of CDK1 alleviated the promoting effects of ZNF655 overexpression in pancreatic cancer cells." (PMID 35927248, 2022). "Furthermore, correlation analysis between the expression level of ZNF655 (high and low) and the overall survival of patients with pancreatic cancer (Grade II, III and IV) was performed using Kaplan–Meier survival." (PMID 35927248, 2022). "As a consequence, ZNF655 promoted the malignant behavior of pancreatic cancer cells through CDK1." (PMID 35927248, 2022). "As a transcription factor of Cys2His2 type ZNF, the role of ZNF655 in pancreatic cancer has not been reported." (PMID 35927248, 2022). "Functional recovery experiments were conducted to clarify whether there was a synergistic effect between ZNF655 and CDK1 in pancreatic cancer." (PMID 35927248, 2022). "Furthermore, ZNF655 knockdown resulted in downregulation of CCND1 expression and inhibition of PI3K/AKT signaling pathway in pancreatic cancer cells." (PMID 35927248, 2022).
pulmonary hypertension (1 paper, 2025). Increased pressure within the pulmonary circulation due to lung or heart disorder. "ROC analysis validated their diagnostic effectiveness, with USP32 and ZNF655 exhibiting ROC values above 0.75 in both the experimental and validation datasets, underscoring their significance in pulmonary hypertension diagnosis." (PMID 40924716, 2025). "This approach yielded complex networks, illustrating the intricate regulatory relationships involving USP32 and ZNF655 within pulmonary hypertension pathology." (PMID 40924716, 2025).
severe combined immunodeficiency (1 paper, 2025). Severe combined immunodeficiency (SCID) comprises a group of rare monogenic primary immunodeficiency disorders characterized by a lack of functional peripheral T lymphocytes resulting in early-onset severe respiratory infections and failure to thrive. "ZNF655 has been associated with tumor progression in solid malignancies, while ZNF257 was among the top differentially expressed genes in a recent codon usage bias (CUB) analysis of severe combined immunodeficiency (SCID)-associated genes." (PMID 41488087, 2025).
cancer (3 papers, 2020 to 2022). A tumor composed of atypical neoplastic, often pleomorphic cells that invade other tissues. "Given that apoptosis is one of the biological phenotypes of cancer, this study focused on the effect of ZNF655 knockdown on apoptosis and the expression of apoptosis-related proteins." (PMID 35927248, 2022). "we found that ZNF655, a TF, can affect a variety of functions in a variety of cancers." (PMID 35927248, 2022). "In general, ZNF655 may affect multiple functions of cancer by targeting certain genes." (PMID 35927248, 2022).
tumor (2 papers, 2022 to 2025). "Collectively, these results highlighted that reduced expression of ZNF655 suppressed the tumor growth in vivo." (PMID 35927248, 2022). "Moreover, IHC staining performed on tumor sections from xenografts showed that ZNF655 and CDK1 expression level was markedly reduced in the ZNF655 knockdown group compared with the control group." (PMID 35927248, 2022). "Indeed, ZNF655 may affect tumor progression through multiple pathways." (PMID 35927248, 2022).
ZNF655 also shares sentences with these, for which no sentence is quoted: Huntington disease (1 paper); non-alcoholic fatty liver disease (1); non-small cell lung carcinoma (1); Parkinson (1).